STAT3 (signal transducer and activator of transcription 3)
Diseases named in the same sentence as STAT3 in open-access papers (continued):
Sharing a sentence is not in itself a finding about the gene and the disease.
Hyperglycemia (continued). "Mice preconditioned with REM have been reported to display a much lower risk of myocardial injury following I/R procedures, whereas hyperglycemia-induced oxidative stress could diminish REM cardioprotection by damaging the Caveolin-3-regulated PI3K/Akt and JAK2/Stat3 signaling pathways." (PMID 34612779, 2021). "Data regarding the kidneys suggest that hyperglycemia may lead to an abnormal metabolism with high hexokinase and pyruvate kinase M2 activity, low Sirtuin-3 levels, an activated STAT3, and HIF1α signaling and an aberrant glycolysis similar to the Warburg effect in cancer cells." (PMID 34778040, 2021). "However, recent results show that lycopene may increase insulin sensitivity and prevent hyperglycemia through inhibition of the STAT-3/SREBP-1c pathway." (PMID 31223502, 2019). "Moreover, several data showed that STAT3 conserves complex I activity in ischemic condition enhancing cell viability and plays an important role in heart protection from chronic stress induced by hyperglycemia." (PMID 30622968, 2018). "STAT3 activation by BNP sustains OPA1-mediated fusion, while FOXO1 competes with STAT3 for 14-3-3 binding, impairing mitochondrial homeostasis under hyperglycemia." (PMID 40866350, 2025). "Our results suggest that FTZ exhibits therapeutic properties against DCM by ameliorating hyperglycemia-induced inflammation and fibrosis via at least partial inhibition of AKT, ERK, and STAT3 signaling pathways." (PMID 34621323, 2021). "In the current study, increased levels of both long and short forms of leptin receptor, as well as, increased levels of GRB2, phospho-STAT3, and phospho-JAK2 were observed under hyperglycemia." (PMID 24260287, 2013). "To confirm the role of hyperglycaemia and its subsequent effects on the development of CNV, we investigated the levels of intracellular ROS formation, STAT3 activation and VEGF production in RPE cells." (PMID 23094067, 2012). "STAT3 regulates beta-cell cycling in the damaged mouse pancreas, guards against DNA damage, and dictates beta-cell apoptosis by modulating PTEN in streptozotocin-induced hyperglycemia." (PMID 39200152, 2024). "Zhuqing Rao reported that hyperglycemia could aggravate liver IRI by inhibiting the polarization of M2 macrophages and IL-10 activation by inhibiting STAT3 through CCAAT/enhancer-binding protein(C/EBP) protein-mediated ER stress." (PMID 36761734, 2023). "However, taking into account a previous report, showing that STAT3 inhibition attenuated PanIN formation in KP mice, we suspect that STAT3 inhibition has the potential to attenuate PanIN progression, which is induced by STZ-induced hyperglycemia." (PMID 32609742, 2020). "Similar with S3I-201, STAT3 knockdown by AAV2/2-shSTAT3 did not affect hyperglycemia and body weight change in STZ-induced diabetic mice." (PMID 31699972, 2019). "Thus, hyperglycemia-induced oxidative stress abrogates RPC cardioprotection by impairing Cav-3-modulated PI3K/Akt and JAK2/STAT3 signaling." (PMID 31583053, 2019). "Hyperglycemia may also contribute to the pathogenesis of AMD by increasing oxidative stress, which activates signal transducer and activator of transcription 3, promotes production of VEGF, and leads to CNV." (PMID 30373222, 2018). "Therefore, we demonstrated that STAT3 activation and expression of CCN2 and fibronectin are enhanced by hyperglycemia in the heart both in vivo and in vitro." (PMID 28672855, 2017). "The hyporesponsiveness to IL10 in the presence of high glucose appears linked to reduced intracellular signal transduction through STAT3, whereas the anti-inflammatory actions of AQX-MN100, a small molecule activator of SHIP1, is not affected by hyperglycemia." (PMID 26883847, 2016). "Leptin receptor signaling classically utilizes the JAK2/STAT3 signaling pathway; therefore, we assessed the levels of JAK2 and STAT3 activation under high glucose conditions and found that hyperglycemia resulted in increased JAK2 phosphorylation in all cell lines within 72 hr." (PMID 24260287, 2013).
Hyperglycemia (continued). "In other studies, hyperglycemia has been found to significantly increase the expression of pro-inflammatory cytokines (TNF-α, IL-1, IL-4, IL-6), which is followed by the upregulation of NF-κB and the signal transducer and activator of transcription 3 (STAT-3) proteins." (PMID 37373216, 2023). "Thus, we speculated that HXJD might ameliorate hyperglycaemia-induced apoptosis and VEGF in the retinas of diabetic rats through controlling SOCS3 or STAT3 expression." (PMID 29318137, 2017). "Hyperglycemia did not activate ERK, the major Kras effector, but strengthened the phosphorylation of STAT3 and the expression of MYC." (PMID 32609742, 2020). "Therefore, in contradiction with the results of the in vitro experiments, the in vivo experiments confirmed that hyperglycemia did not affect the expression of p-JAK2, p-STAT3, CAV-1, and p-NR2B." (PMID 30830585, 2019).
pancreatic ductal adenocarcinoma (73 papers, 2012 to 2026). An infiltrating adenocarcinoma that arises from the epithelial cells of the pancreas. "IL-6/Stat3 have also been implicated in pancreatic ductal adenocarcinoma (PDAC), and paracrine IL-6/Stat3 signaling was shown to regulate the effects of PSCs in matricellular fibrosis and tumor progression." (PMID 35211358, 2022). "The activation of STAT3 in pancreatic ductal adenocarcinoma is associated with autocrine and/or paracrine epidermal growth factor receptor signalling, since the selective inhibition of epidermal growth factor receptor results in a loss of activated STAT3 expression." (PMID 37108193, 2023). "A recent work by our group revealed that NEAT1_1 can regulate STAT3 signaling in pancreatic ductal adenocarcinoma by stabilizing the STAT3 protein via direct binding." (PMID 40170567, 2025). "STAT3, a key oncogene with dual roles in signal transduction and transcriptional activation, has been identified as a positive regulator of ferroptosis in pancreatic ductal adenocarcinoma (PDAC) cell lines." (PMID 40165005, 2025). "The signal transducer and activator of transcription 3 (STAT3) pathway drives pancreatic ductal adenocarcinoma (PDAC) progression by coordinating cellular responses to stress and inflammation." (PMID 40701148, 2025). "A growing body of evidence has shown that STAT3 or GSK3β activation promotes tumor development and progression, as well as gemcitabine resistance in pancreatic ductal adenocarcinoma (PDAC)." (PMID 38555280, 2024). "For example, circARFGEF2 sponged miR-1205 and promoted the activation of JAK2, which phosphorylated STAT3 to trigger pancreatic ductal adenocarcinoma lymphangiogenesis and lymph node metastasis." (PMID 38641828, 2024). "CTSB and STAT3 also participate in regulating alkaliptosis in human pancreatic ductal adenocarcinoma cells, suggesting potential interaction between ferroptosis and alkaliptosis through STAT3 or pH-dependent mechanisms." (PMID 38844964, 2024). "These include STAT3, multidrug resistance, pancreatic ductal adenocarcinoma, pan-cancer analysis, preclinical evaluation, ionizing radiation, and gold nanoparticles." (PMID 38173726, 2023). "Interleukin 6 (IL-6), Oncostatin M (OSM), and downstream effector STAT3 are pro-tumorigenic agents in pancreatic ductal adenocarcinoma (PDAC)." (PMID 36495330, 2023). "PRDX1 deletion has an impact on biological pathways critical to the survival of pancreatic ductal adenocarcinoma cells, as well as STAT3 and autophagy." (PMID 37227568, 2023). "IL-6-induced STAT3 phosphorylation in pancreatic ductal adenocarcinoma (PDAC) was suppressed by blocking IL-6R leading to the attenuation of STAT3 activation in TME toward enhanced sensitivity of cancer cells to chemotherapy." (PMID 36091805, 2022). "On the contrary, GPR87 activates JAK2/STAT3 to form a positive feedback loop to promote the stemness of pancreatic ductal adenocarcinoma cells." (PMID 35651786, 2022). "Recently, it has been shown that IGFBP2 induces selective polarization of pancreatic ductal adenocarcinoma macrophages via the STAT3 pathway, which leads to the macrophage-based immunosuppressive microenvironment in PDAC and thus promotes tumor progression." (PMID 35989938, 2022). "STAT3 is not necessary for the pancreas to develop normally; however, the majority of pancreatic ductal adenocarcinomas (PDA) demonstrate ubiquitous STAT3 expression." (PMID 36497125, 2022). "Signaling pathways involving signal transducer and activator of transcription 3 (STAT3) play key roles in the aggressiveness of pancreatic ductal adenocarcinoma (PDAC), including their tumorigenesis, invasion, and metastasis." (PMID 35565185, 2022). "Among the human pancreatic ductal adenocarcinoma (PDAC) cell lines, signal transducer and activator of transcription 3 (STAT3) are implicated in ferroptosis through modulating the production of cathepsin B." (PMID 35408533, 2022).
pancreatic ductal adenocarcinoma (continued). "Immunofluorescence analysis showed reduced STAT3 nuclear entry after KPNA2 knockdown in pancreatic ductal adenocarcinoma cells." (PMID 36578083, 2022). "The signal transducer and activator of transcription 3 (STAT3) activation correlate with the aggressiveness of pancreatic ductal adenocarcinoma (PDAC)." (PMID 35565185, 2022). "Recently, suppressive M-MDSCs from pancreatic ductal carcinoma patients were characterized as STAT3+/ARG1+/CD14+ cells with a distinct gene signature in which STAT3 has a main role in driving MDSC function." (PMID 35069595, 2021). "UBE2S was demonstrated to promote the epithelial-mesenchymal transition (EMT) through the VHL/HIF-1α/STAT3 signaling pathway in pancreatic ductal adenocarcinoma." (PMID 34535173, 2021). "Preclinical studies strongly suggest significant efficacy of drugs targeting GP130/JAK/STAT3 in the treatment of pancreatic ductal adenocarcinoma and that these molecules are effective chemosensitizers." (PMID 34138876, 2021). "MDSCs present in patients with pancreatic ductal carcinoma were found to be regulated by STAT3, and those with higher frequencies of STAT3+ MDSCs were correlated with shorter overall survival." (PMID 34065010, 2021). "A previous study showed that KLF5 disruption reduces STAT3 activation and tumor growth of pancreatic ductal adenocarcinoma in vivo." (PMID 33424607, 2020). "Pharmacological or genetic inhibition of STAT3 could block erastin-induced ferroptosis in pancreatic ductal adenocarcinoma (PDAC) cells." (PMID 39975542, 2025). "A recent study demonstrated that 94% of normal pancreatic tissues expressed STAT3 and in most cases Y705-STAT3 was moderately or strongly stained; in contrast, only 43% of pancreatic ductal adenocarcinoma samples expressed STAT3, which was generally weakly stained on the Y705 residue." (PMID 37190183, 2023). "IGFBP2 promotes tumor progression in pancreatic ductal adenocarcinoma through the STAT3 pathway." (PMID 35203526, 2022). "The activating factor for ferroptosis may be signal transducer and activator of transcription 3 (STAT3), as demonstrated in pancreatic ductal adenocarcinoma cell lines." (PMID 36611913, 2022). "Similarly, TAMs can directly induce the stem cell-like properties and chemoresistance of pancreatic duct adenocarcinoma by activating signal transducer and activator of transcription 3 (STAT3) signal." (PMID 33898430, 2021). "Circumvention of oncogene-induced cellular senescence, in pancreatic ductal adenocarcinoma cells, has been shown to be accompanied by re-activation of signal transducer and activator of transcription 3 (STAT3), an increased reliance on mitochondrial functions and acquisition of stem cell properties." (PMID 34073600, 2021). "Though only a few trials have shown the efficacy in a clinical setting, the STAT3 pathway remains a promising drug target for future treatment of pancreatic ductal adenocarcinoma and may help overcome chemotherapy resistance." (PMID 34138876, 2021). "In addition, in pancreatic ductal adenocarcinoma cells, interleukin-6-mediated Stat3 activation induced Nrf2 signaling to promote EMT)." (PMID 28758930, 2017). "Likewise, STAT3 is constitutively activated in the majority of pancreatic ductal adenocarcinomas, and appears to be required for the initiation and progression of KRAS2-induced pancreatic tumorigenesis." (PMID 26972355, 2016). "In pancreatic ductal adenocarcinoma (PDAC), MET reduced LAG3 and STAT3 levels, and increased overall survival." (PMID 40520013, 2025). "Using a conceptual framework of pancreatic ductal adenocarcinoma, we show that cancer cells that survive CRISPR-mediated ablation of mutant KRAS are dependent on STAT3 function to maintain tumorigenicity." (PMID 40859018, 2025). "Systematic proteomic analysis revealed that STAT3 activation and concomitant production of LIF play a promotive role in pancreatic ductal adenocarcinoma development." (PMID 40416597, 2025).
pancreatic ductal adenocarcinoma (continued). "Pancreatic ductal adenocarcinoma (PDAC) is one of the most lethal cancers and several studies demonstrate that STAT3 has critical roles throughout the course of PDAC pathogenesis." (PMID 39412616, 2025). "Since we used pancreatic ductal adenocarcinoma (PDA) model for functional analyses, the expression of STAT3 in PDA and correlation with overall survival are also shown." (PMID 38326371, 2024). "In mouse models of pancreatic ductal adenocarcinoma (PDAC), inhibiting STAT3 in the tumor resulted in stromal remodelling." (PMID 38424636, 2024). "For pancreatic ductal adenocarcinoma, it is rather common (30–100%) to express one of the STAT family proteins, namely, STAT3." (PMID 37108193, 2023). "During the expansion of pancreatic ductal adenocarcinoma stem cells, the promoter of G protein-coupled receptor 87 (GPR87) is directly bounded by STAT3 to increase its expression." (PMID 35651786, 2022). "The signal transducer and activator of transcription 3 (STAT3) as a transcription factor and constitutive activation of SATA3 by phosphorylation of Tyr70S were reported in several human tumors, such as pancreatic ductal adenocarcinoma." (PMID 35154607, 2021). "In summary, the present study suggested the novel therapeutic strategy of pterostilbene combined with chloroquine against the growth of pancreatic ductal adenocarcinoma by inhibiting autophagy and downregulating the RAGE/STAT3 signaling pathways." (PMID 34771150, 2021). "Using NetRank, we identified seven genes (STAT3, FOS, JUN, SP1, CDX2, CEBPA, and BRCA1) as most relevant for predicting survival in patients with pancreatic ductal adenocarcinoma." (PMID 22615549, 2012). "Silenced YY1 promotes cell migration and invasion in pancreatic ductal adenocarcinoma by binding to the promoter region of Feline sarcoma-related (FER) and regulating signal transducer and activator of transcription 3 (STAT3)/matrix metallopeptidase 2 (MMP2) signaling pathway." (PMID 34818994, 2021). "The treatment of pancreatic ductal adenocarcinoma (PDAC) remains a huge challenge, because pro-survival signaling pathways—such as the receptor for advanced glycation end products (RAGE)/signal transducer and activator of transcription 3 (STAT3) pathway—are overexpressed in PDAC cells." (PMID 34771150, 2021). "In pancreatic ductal adenocarcinoma, application of IL6R blocking antibodies through inhibiting IL6 signaling could shift the tumor microenvironment from a chemoresistant state to a chemosensitive state, which was accompanied with reduced STAT3 activation." (PMID 33714953, 2021). "STAT3 activation may also be involved in regulation of cell cycle progression and anti-apoptotic response and had been reported to be inactivated by combined HDAC and BET inhibition in pancreatic ductal adenocarcinoma." (PMID 29312470, 2018).
Cachexia (68 papers, 2011 to 2026). Severe weight loss, wasting of muscle, loss of appetite, and general debility related to a chronic disease. "Studies in rodents have elucidated a close association between the IL-6/IL-6R/STAT-3 cascade and muscle degradation during cachexia progression." (PMID 39703501, 2024). "We also previously showed that cachexia-associated adipose loss induced by IL-6 family cytokines is suppressed with systemic JAK inhibition that leads to a decrease in host tissue STAT3 activation." (PMID 37092555, 2023). "Previously, we demonstrated that cachexia-associated adipose loss induced by IL-6 family cytokines is associated with white adipose tissue STAT3 phosphorylation." (PMID 37092555, 2023). "The cachexia phenotype is causally associated with the cytokine-activated transcription factor STAT3, which contributes to symptoms including skeletal muscle atrophy, cardiac dysfunction, and hypothalamic inflammation." (PMID 36091226, 2022). "STAT3 activation has been shown to be a critical transcription factor that is causally linked to cachexia phenotypes such as skeletal muscle wasting, cardiac dysfunction, and hypothalamic inflammation." (PMID 36230949, 2022). "The IL-6/STAT3 signaling pathway induces a loss of muscle mass in experimental cachexia models via two pathways, where on the one hand, STAT3 phosphorylation leads to activation of hepatic acute phase protein gene expression." (PMID 33158194, 2020). "Recent studies have uncovered how STAT3 signaling engages the muscle specific proteolytic pathways in cachexia to induce muscle mass loss." (PMID 30081609, 2018). "Studies in the C26 cancer cachexia mouse model suggested an association between elevated adipose tissue mobilization and increased STAT3 phosphorylation that also coincided with increased ATGL expression levels." (PMID 30081609, 2018). "While IL-6 can activate numerous cellular signaling pathways, the phosphorylation of immediate downstream target signal transducer and activator of transcription 3 (STAT3) has been most widely examined with cachexia-induced muscle mass loss." (PMID 28785374, 2017). "Instead, our data suggest that improvement of cachexia is associated to STAT3 inhibition in muscles by sunitinib." (PMID 25460504, 2015). "Within the nucleus, phosphorylated STAT3 regulates genes associated with inflammation, muscle protein degradation, and adipose tissue loss, exacerbating the imbalance between muscle synthesis and degradation that characterizes cachexia." (PMID 40704145, 2025). "Our findings collectively define how cytokines contribute directly to cachexia-associated adipose wasting through STAT3-dependent transcriptional changes that ultimately increase adipocyte lipolysis through ATGL and CGI-58 activity, providing new potential targets to suppress cancer cachexia." (PMID 35785158, 2022). "Furthermore, cachexia-associated cytokines that used STAT3 to induce lipolysis were primarily dependent on the lipase ATGL and its cofactor CGI-58 rather than lipases HSL and MAGL." (PMID 35785158, 2022). "Imperatorin is another promising agent to treat muscle loss in the context of cachexia, as it selectively inhibits the Stat3 (signal transducer and activator of transcription 3)-dependent atrophy-signaling pathway, by downregulating skeletal muscle atrogene expression, such as Fbxo32." (PMID 33114658, 2020). "Moreover, based on the fact that STAT3 is one of the responsible mechanisms of cancer-associated cachexia, our results, which have shown suppressed STAT3 activation by VA, offer another reason to support our conclusion." (PMID 32722030, 2020). "In cachexia and chronic kidney disease models, both of which exhibit muscle mass loss, STAT3 initiated muscle wasting by stimulating CCAAT/enhancer binding protein (C/EBPδ) expression and activity, which in turn increased myostatin, MAFbx/Atrogin-1, and MuRF-1 expression in myofibers." (PMID 31114509, 2019).